IL10 (interleukin 10)
Diseases named in the same sentence as IL10 in open-access papers (continued):
Sharing a sentence is not in itself a finding about the gene and the disease.
tuberculosis (183 papers, 2008 to 2025). A chronic, recurrent infection caused by the bacterium Mycobacterium tuberculosis. "Association of IL-10 (-1,082 A/G) SNPs with demographic and clinical parameters in healthy controls and tuberculosis patients infected with SIT745/EAI1-MYS and non-SIT745/EAI1-MYS M. tuberculosis strains." (PMID 40487054, 2025). "This study aimed to investigate the role of IFN-γ (+874) A/T and IL-10 (−1,082) A/G SNPs with tuberculosis (TB) disease susceptibility among patients infected with M. tuberculosis SIT745/EAI1-MYS strain." (PMID 40487054, 2025). "Previous studies in humans and mice have shown that IL-10 responses and genetic polymorphisms are associated with the development of tuberculosis." (PMID 38665909, 2024). "Phenotypic and functional changes in adaptive and innate immune cells provide a complex picture of tuberculosis pathognomonic mechanisms potentially caused by aberrantly high IL-6 and IL-10 levels." (PMID 34035497, 2021). "In mice, overexpression of IL-10 is associated with increased bacterial burdens, while in humans with tuberculosis, elevated levels of IL-10 have been associated with more active disease and more severe clinical signs." (PMID 34026898, 2021). "In the present study, the role of interleukin-10 and 13 in a tuberculosis-associated pulmonary dysfunction was investigated." (PMID 31363402, 2019). "In clinical practice, an increased susceptibility toward the development of progressive tuberculosis in humans with increased IL-10 levels was reported." (PMID 31281230, 2019). "Genome-wide association studies in humans have linked IL10 polymorphisms to susceptibility and resistance towards tuberculosis, although the results vary depending on the polymorphism studied and the study subjects." (PMID 29985419, 2018). "For rs1518111 in IL10, under the log-additive model, we found that individuals with risk allele C had a greater risk of tuberculosis than carrying wild alleles increased by 79% (OR = 1.79, 95% CI = 1.49–2.14, p = 5.04E-10)." (PMID 29662655, 2018). "The participation of IL-10 in the formation of granuloma in tuberculosis requires further studies, since this cytokine is associated with the clinical cure of the disease and in the repertoire of antigen-specific T cells against M. tuberculosis." (PMID 29543912, 2018). "For rs3021094 in IL10, we found that the minor allele “G” protect the risk of tuberculosis in the log-additive model (OR = 0.34, 95% CI = 0.28–0.42, p = 3.31E-24)." (PMID 29662655, 2018). "A number of IL-10 single nucleotide polymorphisms have been found to be associated with both IL-10 inducibility and susceptibility to infectious diseases such as tuberculosis and neurosyphilis." (PMID 28143443, 2017). "Low disease severity was associated with a pro-inflammatory cytokine profile, whereas severe tuberculosis was associated with enhanced IL-10 production." (PMID 28575063, 2017). "Although interferon-gamma, interleukin-10, and adiponectin are key immunopathogenesis mediators of tuberculosis, their association with clinical manifestations of early stage disease is inconclusive." (PMID 26880909, 2016). "The present study was aimed to evaluate the levels of TNF-α, IL-10 & IL-6 cytokines and their correlation with genotype variants amongst tuberculosis patients and their household contacts." (PMID 26359865, 2015). "Recently, two meta-analysis also showed that IL10 –819C>T and -592C>A were associated with tuberculosis." (PMID 26340474, 2015). "A number of observational studies have been conducted to investigate the association of IL-10 gene polymorphisms with tuberculosis (TB) susceptibility." (PMID 24523896, 2014). "Others have found another anti-inflammatory genetic variant associated with a higher IL-10 production capacity to be more prevalent among tuberculosis patients compared with healthy controls in Gambia." (PMID 25040424, 2014).
tuberculosis (continued). "Published data suggests that IL-10 inhibits synthesis of IFN-γ by T cells and that production of IL-10 has been associated with anergy in tuberculosis." (PMID 23634300, 2013). "Macrophage deactivation by IL-10 has been shown to exacerbate disease and to be associated with reactivation of tuberculosis in humans and mice." (PMID 23110184, 2012). "Overproduction of IL-10 associated with concurrent PbNK65 infection is therefore likely to exacerbate the outcome of tuberculosis by interfering with macrophage associated bacterial clearance." (PMID 23110184, 2012). "In addition to the assumed pathogenic role of IL10 in tuberculosis disease progression, the protective roles of the pro-inflammatory cytokines TNFα and IL1β have been well documented by in vivo murine models, and for IL1β in hMDMs." (PMID 32477344, 2020). "Furthermore, among others, SNPs in Interleukin 1β (IL1B), IL12, IFNG, Interleukin 10 (IL10) and Tumor Necrosis Factor α (TNFα) genes were described in relation with risk to tuberculosis disease." (PMID 29361774, 2018). "The study found that IL10 gene associated with the risk of tuberculosis." (PMID 29662655, 2018). "In this study, we therefore hypothesized that IL-10 and its homologs may be deficient and that this immune dysregulation may be involved in the immunopathology associated with tuberculosis-IRIS." (PMID 23303806, 2013). "Moreover, in an animal model of tuberculosis, the deficiency of IL-10 reduced bacterial load in lungs with decreased dissemination to the spleen, which was preceded by an earlier and enhanced Th1-type response." (PMID 23239994, 2012). "Similarly polymorphisms in IL10 linked to high and low producer phenotypes have shown conflicting associations with tuberculosis disease susceptibility and disease severity in different patient populations." (PMID 19274101, 2009). "Malfunction in the IFN-γ and IL-10 genes may undermine the host’s capability to mount an efficient response to M. tuberculosis infection, heightening susceptibility to the disease and increasing the likelihood of developing active tuberculosis." (PMID 40487054, 2025). "Furthermore, high levels of IL-10 were associated with susceptibility to tuberculosis." (PMID 36671466, 2022). "Increased control of M. tuberculosis infection was observed in T cell–specific Il10-deficient mice, closely resembling the phenotype observed in complete Il10-deficient mice, indicating that T cells are the critical source of IL-10–induced TB susceptibility." (PMID 28584007, 2017). "To date, there is limited information on the specific cellular sources of IL-10 during the course of M. tuberculosis infection and their relative contribution to host susceptibility to TB (reviewed in Refs." (PMID 28584007, 2017). "Together, our data reveal that, despite the multiple immune sources of IL-10 during M. tuberculosis infection, activated effector T cells are the major source accounting for IL-10–induced TB susceptibility." (PMID 28584007, 2017). "Conversely, the immunosuppressive cytokine IL-10 has been reported to limit the protective immune response to M. tuberculosis infection, contributing to increased susceptibility to TB." (PMID 28584007, 2017). "IL-10 has been shown to impair immune responses to M. tuberculosis infection, contributing to host susceptibility to TB." (PMID 28584007, 2017). "Further evidence for a detrimental role of IL-10 during M. tuberculosis infection arose from the findings that overexpression of IL-10 increases host susceptibility to TB by limiting Th1 cell responses and macrophage bactericidal functions." (PMID 28584007, 2017). "The specific cellular sources of IL-10 during M. tuberculosis infection that can contribute to TB susceptibility are still undetermined." (PMID 28584007, 2017). "The higher levels of IL-10 may represent compensatory antiinflammatory and immune-regulatory responses, whereas elevated IL-22 levels suggest an association with immunopathology in tuberculosis-IRIS." (PMID 23303806, 2013).
tuberculosis (continued). "Therefore, this study aimed to investigate the association of IFN-γ +874 A/T and IL-10 −1,082 G>A SNPs with TB disease susceptibility among patients infected with the Malaysia-specific M. tuberculosis strain, SIT745/EAI1-MYS." (PMID 40487054, 2025). "Serum levels of IFN-γ, TNF-alpha, and IL-10 were significantly elevated before treatment in tuberculosis patients and decreased significantly post-treatment." (PMID 40276432, 2025). "utilized machine learning techniques and found that among HIV-positive patients, those with tuberculosis exhibited significantly elevated levels of inflammatory markers including IL-2, IL-4, IL-6, IL-10, TNF-α, and IFN-γ." (PMID 41322408, 2025). "We measured both IFN-γ and IL-10 levels with ELISA in 26 tuberculosis patients and 28 latent tuberculosis subjects." (PMID 39257584, 2024). "The panel we employed included cytokines that are elevated in tuberculosis, i.e., interferon gamma (IFNγ), IL-2, IL-5, IL-10, IL-17, GM-CSF and TNFα." (PMID 38415011, 2024). "IL-10 is known to exacerbate tuberculosis by inhibiting the protective arm of innate immune response and antigen-specific cellular immune response." (PMID 39003443, 2024). "The overexpression of ISG15 is observed in human monocytes during tuberculosis, and it plays a role as a cytokine that induces IL-10 secretion." (PMID 39062562, 2024). "Six of seven cytokines were significantly higher in tuberculosis patients as compared to contacts and four of these (i.e., IL-6, IP-10, IL-10, and IL-22) were detectable in the majority of tuberculosis patients." (PMID 35759173, 2023). "Recently, we described aberrant high plasma levels of specific cytokines (i.e., IL-6, IP-10, IL-10, IL-22) in tuberculosis patients." (PMID 36650358, 2023). "In this study, we analyzed the concentrations of selected plasma cytokines (i.e., IL-6, IP-10, IL-10, IL-22, IFNγ, GM-CSF, IL-8) and M. tuberculosis sputum burden in patients with tuberculosis (n = 76)." (PMID 35759173, 2023). "IL-6 showed the strongest discriminating capacity for tuberculosis disease and in combination with IL-10 concentrations efficiently classified paucibacillary tuberculosis cases as well as those with fatal disease outcome." (PMID 35759173, 2023). "However, IL-10 may be involved in the mutual regulation of the levels of CSF-2 and CSF-3 to balance the levels of these three cytokines, which is associated with the risk of tuberculosis." (PMID 37818041, 2023). "The mouse tuberculosis model revealed an increased count of IL-35- and IL-10-co-producing regulatory B-cells." (PMID 37626620, 2023). "Own previous studies provided evidence that aberrant high serum cytokines (i.e., IL-6, IL-10) in tuberculosis can affect T-cell functions, e.g., by causing constitutive STAT3 phosphorylation, in tuberculosis patients." (PMID 35759173, 2023). "Combinations of different plasma cytokine (namely, IL-6, IL-10, and IP-10) efficiently classified tuberculosis patients with differential mycobacterial burden and especially IL-6 qualified as a biomarker candidate for early treatment response." (PMID 35759173, 2023). "Previously, we demonstrated that aberrant high serum IL-6 and IL-10 concentrations affected T-cell functions in tuberculosis patients." (PMID 35759173, 2023). "Th2 cytokines, i.e., IL-4, IL-6, IL-10, IL-13, etc., inhibit Th1 responses and thus cross-regulate and influence the progression to active tuberculosis." (PMID 36776550, 2022). "Regulatory B cells produce TGF-β and IL-10, important in colitis, arthritis and allergic airway inflammation and tuberculosis." (PMID 34220793, 2021). "For example, the IL-10 locus contains an NF-κB binding motif that enhances IL-10 transcription in macrophages, cells with a critical, early involvement in tuberculosis pathogenesis." (PMID 33658385, 2021). "We selected TNFα and IL-10 because both are key mediators for orchestrating the immune response in human tuberculosis." (PMID 34149713, 2021).
tuberculosis (continued). "IFNγ and IL10 have been suggested as biomarkers for parasitic and other infections, such as tuberculosis." (PMID 33767693, 2021). "In tuberculosis macrophage-derived TNFα and IL-10 play a special role and the balance between these mediators affect the outcome of tuberculosis infection." (PMID 34149713, 2021). "Two of these polymorphisms are microsatellite repeats of (GT)n, where allele two at this locus is associated with susceptibility to tuberculosis and reduced expression of SLC11A1 mRNA and increased anti-inflammatory Interleukin 10 (IL-10)." (PMID 34485444, 2021). "For example, in viral pneumonia and tuberculosis, neutrophils are suppliers of IL-10 but the substantial production of this cytokine is produced by interstitial macrophages and T cells." (PMID 33995357, 2021). "Treatment of Mtb-infected macrophages with the prolyl-hydroxylase inhibitor Molidustat reduced the release of TNFα and IL-10, two key cytokines involved in the immune response in tuberculosis." (PMID 34149713, 2021). "The finding that the level of IL-10, a cytokine with immune regulatory functions, correlates with IL-6 expression and serum levels in tuberculosis is seemingly controversial." (PMID 34035497, 2021). "IL-10 and IFNα are important for treating tuberculosis, and the decreased expression of IL-10 and IFNα can lead to a significant impairment of antimicrobial activity." (PMID 33193291, 2020). "This has been extensively studied in mouse models of tuberculosis, where both IL-10-dependent and -independent mechanisms have been identified." (PMID 32101732, 2020). "In algorithms combining young age, positive skin test results, and elevated CFPS TNF-α, IFN-γ, and IL-10 responses, the positive predictive values for co-prevalent and incident tuberculosis were 40 and 25%, respectively." (PMID 32736606, 2020). "In contrast, our study showed that the levels of IL10 were lower in PTB patients than in any other form of tuberculosis." (PMID 32962082, 2020). "For example, IFN-γ, TNF-α, and IL-10 expression is increased in Asian elephants seropositive for tuberculosis, and TNF-α and IFN-γ are upregulated in in vitro stimulated immune cells from elephants with EEHV." (PMID 32992555, 2020). "The dual functions of FOXO3 as an inducer of macrophage apoptosis and inhibitor of IL-10 secretion, suggest that this factor can be proposed as a new target for host-directed therapy against Tuberculosis." (PMID 31921181, 2019). "tuberculosis must be developed to identify the roles of IL-10 and other lesser-studied cytokines involved in mycobacterial growth restriction in resisters, providing insights for the potential of cytokine manipulation as a preventive therapeutic strategy." (PMID 31602294, 2019). "Serum levels of IL-10 showed significant upregulation in patients with normal and downregulation with obstructive spirometry alongside tuberculosis treatment in our study." (PMID 31363402, 2019). "It seems that the low levels of interleukin 10 play an essential role in the emergence of tuberculosis related obstructive and also restrictive pulmonary dysfunction." (PMID 31363402, 2019). "Based on significant reduction of IL-10 in tuberculosis patients with obstructive spirometry in our study, it can be concluded that IL-10 plays a central role in preventing respiratory dysfunction." (PMID 31363402, 2019). "Since tuberculosis is considered as a risk factor for COPD, change in IL-10 can be raised to the development of post tuberculosis lung dysfunction." (PMID 31363402, 2019). "One of these studies was an outpatient cohort study that followed participants with HIV-associated tuberculosis and showed that higher pre-ART levels of MCP-1/CCL2, eotaxin, IL-10, TNF-α, and IL-6 were associated with 6-month mortality." (PMID 31276515, 2019).
tuberculosis (continued). "The presence of IL-10-secreting tolerogenic DCs would correlate with the permissive immune microenvironment of both lepromatous leprosy and tuberculosis and warrants further investigation of their role in disease pathogenesis." (PMID 31167948, 2019). "IL-10 and IL-13 are two cytokines that undergo changes in the course of tuberculosis and can be raised in pathogenesis of lung dysfunction." (PMID 31363402, 2019). "Through the literature search, we found that interleukin gene is related to the occurrence of tuberculosis, few studies have explored the association between IL4, IL6, and IL10 polymorphisms and PTB risk in Chinese populations." (PMID 29662655, 2018). "The effects of interleukin gene (IL4, IL6, IL10) on tuberculosis were assessed by logistic regression analysis under three genetic models, including dominant, recessive and log-additive models." (PMID 29662655, 2018). "The study found that butyrate suppressed the tuberculosis-induced proinflammatory cytokine responses, while it increased production of IL-10, an immune regulatory cytokine." (PMID 29204120, 2017). "G/G polymorphism of the IL-10-1082 has been reported to be a protecting factor against pulmonary diseases and especially acute RDS and active tuberculosis." (PMID 28298812, 2017). "Increased frequencies of FoxP3+, IL-10-, and TGFβ-releasing Tregs have been found in peripheral blood and at the site of infection in tuberculosis patients." (PMID 29312298, 2017). "Interferon-gamma levels (P < 0.0001) and interferon-gamma to interleukin-10 (P < 0.001) and interferon-gamma to adiponectin (P = 0.027) ratios were elevated in tuberculosis cases." (PMID 26880909, 2016). "Serum IL-37 was positively correlated with IL-10 and negatively correlated with IL-12 in patients with tuberculosis." (PMID 26435567, 2015). "Some studies indicate that there are higher levels of IL-10 in active tuberculosis, but Sahiratmadja and colleagues showed that this increase happens only after clinical cure." (PMID 26495323, 2015). "As an update to other recent meta-analyses, the purpose of this study was to explore whether interleukin-10 (IL-10) polymorphisms and their haplotypes contribute to tuberculosis (TB) susceptibility." (PMID 26030829, 2015). "Gerosa and colleagues have previously shown that there is concomitant production of IFN-γ and IL-10 by Th1 lymphocytes as well as by memory T cells in bronchoalveolar lavage fluid obtained from patients with active tuberculosis." (PMID 26495323, 2015). "With regard to the dynamics of IL-10 production in tuberculosis active disease and after clinical cure, the results are conflicting." (PMID 26495323, 2015). "In fact, among tuberculosis patients, enhanced levels of serum IL-10, in vitro cytokine production, increased expression of Treg cells (CD25+FOXP3+), and inhibition of the Th1 response were recently observed." (PMID 25992795, 2015). "Pereira and colleagues found that, in addition to an enhancement in the production of TNF-α, patients with systemic manifestations of tuberculosis have increased production of IL-10." (PMID 26495323, 2015). "This group also found that Tregs from tuberculosis patients not only suppress IFN-γ production but also inhibit IL-10 production by CD4+ T cells." (PMID 25969837, 2015). "Among them, the most important receptor is TLR2 which is involved in the production of IL-10 during tuberculosis." (PMID 24695099, 2014). "Other human studies on tuberculosis have suggested that IL-10 also has a critical role in protecting the host against inflammatory immunopathology." (PMID 24558401, 2014). "Nevertheless, IL-10 is clearly an important regulatory mechanism in tuberculosis, with the ability to modulate the different arms of CD4+ T immunity." (PMID 23544075, 2013). "IL-10 mRNA was highly and significantly induced in tuberculosis-IRIS patients at 6 hours and more so at 24 hours (P = .04 and P = .0002, respectively)." (PMID 23303806, 2013).